UCHL1 (ubiquitin C-terminal hydrolase L1)
Diseases named in the same sentence as UCHL1 in open-access papers (continued):
Sharing a sentence is not in itself a finding about the gene and the disease.
injury (20 papers, 2011 to 2025). Damage inflicted on the body as the direct or indirect result of an external force, with or without disruption of structural continuity. "Ubiquitin C‐Terminal Hydrolase L1 (UCH‐L1), when detected in blood after brain injury, has been associated with neurological decline and unfavorable outcomes in TBI patients." (PMID 39302033, 2024). "The level of UCHL1 was reported to be increased in serum and the CSF after traumatic brain injury and to be associated with the severity of injury and long-term outcome." (PMID 39272777, 2024). "Currently, many researchers agree that UCHL1 is a well-accepted serum biomarker for severe traumatic brain injury (TBI)." (PMID 40141757, 2025). "For example, proteomic data from only 4‐Plex assay (NfL, GFAP, tau protein, and ubiquitin c‐terminal hydrolase L1; UCH‐L1) better classified people with traumatic brain injury when compared to only single proteomic measure." (PMID 38234075, 2024). "UCHL-1 levels in both children with mild head trauma and the control group were below the detection limit of the assay kit." (PMID 32987792, 2020). "Correlation with lesion volume is seen in other neurological disorders as well; in a recent study of 197 patients with traumatic brain injury, serum measurements of GFAP, NFL, tau and UCHL1 correlated with lesion volume on MRI." (PMID 35765081, 2022). "The temporal profiles for serum UCHL1 and GFAP are mostly in line with the limited literature on SRC and mild traumatic brain injury, with studies to date indicating UCHL1 increases are only seen acutely (i.e. within hours) and GFAP primarily within the first 24 h of injury." (PMID 33422120, 2021). "UCHL-1 and IL-11 are not useful markers in the case of mild head trauma because their concentrations did not change in comparison to the control group." (PMID 32987792, 2020). "When obtained within 6 h of injury UCHL1 in combination with GFAP was very sensitive for a positive head CT, and was thought to provide the objective evidence clinicians desire when trying to reduce the use of CT scans in patients with mild traumatic brain injury." (PMID 27468268, 2016). "They found that UCHL1 levels were significantly higher in patients with complicated mild TBI (mTBI) compared to those with uncomplicated mTBI and in patients with mTBI compared to those without a traumatic brain injury." (PMID 40141757, 2025).
ovarian carcinoma (19 papers, 2014 to 2026). A malignant neoplasm originating from the surface ovarian epithelium. "Various cancers, including colorectal and ovarian cancers, head and neck cancers, pancreatic cancer, and hepatocellular, gastric, and esophageal carcinomas, have been linked to epigenetic silencing of the UCHL1 gene." (PMID 36830563, 2023). "The ubiquitin carboxyl terminal hydrolases UCH37 (also known as UCHL5) and UCHL1 have both been implicated in ovarian cancer." (PMID 25605410, 2015). "UCHL1 knockdown in ovarian cancer cell lines where it was overexpressed caused increased proliferation." (PMID 25605410, 2015). "Five of the 10 most down-regulated genes, Aldh1a2, Enpp2, Lgfbp5, Thbd, and Uchl1, have been previously implicated in ovarian cancer." (PMID 24672774, 2014). "To determine whether the cytotoxicity of 6RK73 in ovarian cancer is linked to UCHL1 inhibition, we examined the function of UCHL1 in ovarian cancer cells." (PMID 41584043, 2026). "This suggests that UCHL1 is related to the stemness of ovarian cancer cells, but its specific mechanism requires further investigation." (PMID 36424614, 2022). "For example, the level of UCHL1 is negatively related to cisplatin resistance in ovarian cancer, and knockdown of UCHL1 promotes cisplatin resistance." (PMID 33718207, 2021). "Positive regulation of apoptotic process is a cell death term, and is enriched in genes regulated by Ubiquitin carboxyl terminal hydrolase 1 (UCHL1), which is a putative tumor suppressor in ovarian cancer." (PMID 26138921, 2015). "In ovarian cancer, UCHL1 may be one of the markers related to early stages of high-grade serous carcinoma, immunogenicity, and cisplatin resistance." (PMID 36424614, 2022). "Therefore, we hypothesize that the cytotoxic effects of 6RK73 in ovarian cancer cells may occur through a UCHL1-independent mechanism, potentially involving suppression of the AKT1/Sp1/c-Myc signaling axis." (PMID 41584043, 2026). "However, UCHL1 has dual functions, and its role in ovarian cancer remains unclear." (PMID 41584043, 2026). "The high expression of UCHL1 in cervical squamous cell carcinoma, UCHL3 in ovarian cancer, and UCHL5 in lung adenocarcinoma are also used as markers of poor prognosis." (PMID 39034372, 2024). "The expression distribution of 6-OMAGs mRNA in 45 human ovarian cancer cell lines obtained from the CCLE dataset demonstrated that there were large variations in the expression levels of FBN1, TIMP3, and UCHL1 between cell lines." (PMID 36424614, 2022). "Several genes silenced by promoter DNA hypermethylation such as MLH1, SULF1, SFRP, TNFRSF10A, UCHL1, and CLDN4 are related to platinum resistance in ovarian cancer." (PMID 33680048, 2020). "Interestingly, the anti-tumor effects of 6RK73 in ovarian cancer were independent of UCHL1 inhibition." (PMID 41584043, 2026). "In this study, we observed that 6RK73, as a potential anti-cancer agent, significantly inhibited ovarian cancer cell growth and cell cycle progression by attenuating AKT1/ Sp1/c-Myc signaling, independent of UCHL1 inactivation." (PMID 41584043, 2026). "In our study, overexpression of UCHL1 in OVCAR3 and SKOV-3 ovarian cancer cell lines did not significantly affect cell proliferation, suggesting that UCHL1 may play a limited role in this context or that its tumor-suppressive function may require higher expression thresholds." (PMID 41584043, 2026).
prostate carcinoma (18 papers, 2011 to 2026). A carcinoma that arises from epithelial cells of the prostate gland. "Herein, we demonstrate that UCHL1 is associated with genomic DNA in certain prostate cancer cell lines, including DU 145 cells derived from a brain metastatic site, and in HEK293T embryonic kidney cells with a neuronal lineage." (PMID 29126443, 2017). "We identified UCHL1 as a protein cross-linked to DNA in some of the prostate cancer cells, including DU 145, derived from brain metastasis." (PMID 29126443, 2017). "In DU 145 prostate cancer cells, UCHL1 was frequently found at ITSs located in the intron of genes that were either expressed or silent." (PMID 29126443, 2017). "In the case of prostate cancer, comparative proteomic data from prostate cancer cell lines showed that UCHL1 was expressed in androgen insensitive cell lines." (PMID 29126443, 2017). "Both protein and mRNA levels of UCHL1 are down-regulated in prostate cancer due to hypo-methylation of the UCHL1 promoter." (PMID 25605410, 2015). "In summary, we showed that UCHL1 is suppressed in prostate cancer patients by promoter hypermethylation." (PMID 21999842, 2011). "In analogy, the measurement of UCHL1 mRNA levels using quantitative real time PCR confirmed significant downregulation of UCHL1 at transcriptional level in prostate cancer." (PMID 21999842, 2011). "Since downregulation of UCHL1 is a prominent feature of primary prostate cancer cells, we assumed a crucial role for UCHL1 as a potential tumour suppressor." (PMID 21999842, 2011). "In the present study, we analyzed the mechanism of UCHL1 downregulation in PCa and the role of UCHL1 as tumour suppressor in LNCaP prostate cancer cells." (PMID 21999842, 2011). "To analyze expression of UCHL1 in PCa cell lines, we performed semi-quantitative RT-PCR and Western blotting on LNCaP and DU145 cells to investigate the role of expression of UCHL1 in prostate cancer initiation and progression." (PMID 21999842, 2011). "We have previously reported significant downregulation of ubiquitin carboxyl-terminal hydrolase 1 (UCHL1) in prostate cancer (PCa) compared to the surrounding benign tissue." (PMID 21999842, 2011). "Consistent with the findings in hepatocellular carcinoma and prostate cancer, we hypothesized that UCHL1 functions as a tumor suppressor gene in NPC." (PMID 32120844, 2020). "Furthermore, UCHL1 knockdown studies on the androgen insensitive DU 145 cell line demonstrated that UCHL1 promotes prostate cancer metastasis by the induction of epithelial-to-mesenchymal transition (EMT)." (PMID 29126443, 2017). "Furthermore, we present evidences that UCHL1 expression can affect the behavior of prostate cancer cells in different ways." (PMID 21999842, 2011). "Protein profiling revealed significant downregulation of UCHL1 in prostate cancer patients." (PMID 21999842, 2011). "Therefore, the main objective of the present study was the functional characterization of UCHL1 in prostate cancer progression." (PMID 21999842, 2011). "Based on the fact that the UCHL1 expression is regulated via promoter methylation in different types of cancer, we investigated the methylation status of the UCHL1 promoter regions in 20 samples of normal prostate tissue and 20 tissue samples of prostate cancer by MSP." (PMID 21999842, 2011). "Previously, ubiquitin C-terminal hydrolase-L1 (UCH-L1) and ubiquitin C-terminal hydrolase-L3 (UCH-L3) were reported to be involved in prostate cancer cell progression through the epithelial-to-mesenchymal transition (EMT) regulation." (PMID 34745437, 2021). "Indeed, we could observe more cells with an increased level of SA-ß-gal in cells overexpressing UCHL1 compared to the respective mock control cells, suggesting that the overexpression of UCHL1 leads to the induction of cellular senescence in LNCaP prostate cancer cells." (PMID 21999842, 2011).
prostate carcinoma (continued). "Ubiquitin C-terminal hydrolase L1 (UCHL1), a member of the UCH class of DUBs, is one of the most well studied DUBs, and was identified in our prostate cancer protein profiling study." (PMID 21999842, 2011). "Thus, our study supplement substantially the current knowledge of the tumor suppressor functions of UCHL1 in cancer progression and postulate that UCHL1 hypermethylation could be a potential molecular marker for prostate cancer need to be evaluated in large number of patient cohort." (PMID 21999842, 2011). "Moreover, ubiquitin C-terminal hydrolase L1 (UCH-L1) and ubiquitin C-terminal hydrolase L3 (UCH-L3) differentially govern the stem-like traits in prostate cancer cells through regulating the PI3K/AKT pathway." (PMID 36969009, 2023). "As a control, we also performed the UCHL1 ChIP assays with PC-3 prostate cancer cells which do not express UCHL1." (PMID 29126443, 2017). "No DUBs were significantly dysregulated in prostate carcinomas, and only one was found in kidney (UCHL1, downregulated), suggesting that different tumor types display different levels of alteration of the deubiquitination machinery." (PMID 21283576, 2011). "It has been reported that UCHL1 is deregulated in multiple types of tumours and the precise mechanism of the downregulation and function of UCHL1 in prostate cancer progression have not been investigated before." (PMID 21999842, 2011). "In addition, UCHL1 is another key regulator of tumor metastasis, which is highly expressed in metastatic prostate cancer cell lines, but is not detected in weakly metastatic and benign prostate cancer cell lines." (PMID 35884607, 2022). "Immunoblotting with whole cell lysate revealed that p27Kip1 protein levels were significantly elevated in consequence of UCHL1 overexpression in LNCaP prostate cancer cells lines where as the amount of p27Kip1 mRNA was not significantly correlated with protein levels." (PMID 21999842, 2011).
Stroke (18 papers, 2013 to 2025). Sudden impairment of blood flow to a part of the brain due to occlusion or rupture of an artery to the brain. "After adjustment for infarct volume, peak level time points for GFAP and NFL were essentially unaltered, occurring at 77 h (3 days) for GFAP and > 8 days for NFL, t-tau, and UCHL1 after stroke onset." (PMID 40900222, 2025). "Nevertheless, a high correlation between UCHL1 and infarct volume was found 4.7 days after stroke onset, and similar to NFL, remained correlated with acute infarct volume after 90 days." (PMID 40900222, 2025). "Few studies have investigated plasma or serum levels of UCHL1 after stroke." (PMID 40900222, 2025). "We found only one study examining UCHL1 beyond 48 h after stroke." (PMID 40900222, 2025). "It is reasonable to assume that a stroke affecting mainly white matter would give another pattern (e.g. high serum levels of MBP but not tau) than a stroke affecting mostly grey matter in cortex or basal ganglia (e.g. low serum levels of MBP but high levels of UCHL1 and tau)." (PMID 35765081, 2022). "Substantial increase in UCHL1 levels after stroke—measured before, immediately after, and 24 h after EVT—was observed in the patients with unfavorable outcomes; moreover, temporal change in of GFAP and UCHL1 levels were associated with more severe types of hemorrhagic transformation, especially PH." (PMID 34511123, 2021). "Our objective was to determine the diagnostic utility of glial fibrillary acidic protein (GFAP) and ubiquitin C-terminal hydrolase L1 (UCH-L1) in the emergency department to identify and differentiate acute stroke within 4.5 h of symptom onset in patients admitted with a stroke code alert." (PMID 40649119, 2025). "Other brain-specific biomarkers used following stroke include neuron-specific enolase (NSE), tau, neurofilament light chain (NfL), glial fibrillary acidic protein (GFAP), and ubiquitin C-terminal hydrolase L1 (UCH-L1)." (PMID 39968454, 2025). "At the same time, the regulation of the brain protein of UCHL1, Hypoxia-inducible factor 1alpha (HIF-1α, 239) may be crucial for how nerve cells repair themselves after a stroke." (PMID 34325669, 2021). "In a randomized controlled trial investigating the effect of erythropoietin in acute ischemic stroke, a slight increase in UCHL1 during the first three days after stroke was noted in the placebo group but not in the treatment group; however, no imaging data was available." (PMID 40900222, 2025). "Although UCHL1 did not provide useful prognostic information in our study, its level was elevated in the CADASIL patients with stroke, especially the ICH group." (PMID 32321529, 2020).
gastric cancer (16 papers, 2008 to 2025). A primary or metastatic malignant neoplasm involving the stomach. "And UCHL1 was a valuable diagnostic marker for progression of GC while it was also associated with the prognosis of gastric cancer patients." (PMID 26550574, 2015). "our analysis implied that DNA hypomethylation may lead to induce the RDH13 and UCHL1 expression in gastric cancer, whereas DNA hypermethylation is able to cause decreasing expression of CLDN11 in gastric groups." (PMID 34322159, 2021). "Accordingly, it is important to identify the role and mechanism of UCHL1 in gastric cancer progression." (PMID 41155583, 2025). "Reduced UCHL1 expression suppressed cell proliferation, migration, and invasion in gastric cancer cell lines." (PMID 41155583, 2025). "Specifically, in gastric cancer, it has been revealed that overexpression of UCHL1 increases cell proliferation, migration, and invasion by activating the AKT and ERK1/2 tumor growth pathways, a phenomenon dependent on the enzymatic activity of UCHL1." (PMID 40078282, 2025). "The de-ubiquitinase Ubiquitin C-terminal hydrolase-L1(UCHL1) promotes gastric cancer metastasis via the Akt and ERK1/2 pathways." (PMID 26811493, 2016). "Although UCHL1, a deubiquitinating enzyme (DUB), is implicated in the progression of several cancer types, its role in gastric cancer remains unclear." (PMID 41155583, 2025). "The IMAGiC model predicts response to ICI in patients with advanced gastric cancer based on the expression signature of four genes (ubiquitin C-terminal hydrolase L1 [UCHL1], tyrosine kinase 2 [TYK2], protein kinase D1 [PRKD1], and armadillo repeat-containing X-Linked 1 [ARMCX1])." (PMID 37877810, 2024). "UCHL1 promotes gastric cancer progression through Akt and Erk1/2 pathways." (PMID 39605891, 2024). "In other cancer contexts, such as ovarian, hepatocellular and gastric cancers, UCHL1 DNA methylation has been reported, suggesting it may play a role in cancer suppression in these contexts." (PMID 34497382, 2022). "Especially, UCHL1 is significantly upregulated in CAMs, the tissue group of gastric cancers." (PMID 34322159, 2021). "UCHL1 could promote proliferation of B-cell lymphoma and gastric cancer cells; while others demonstrated that UCHL1 induced cell cycle arrest and inhibited tumor cell proliferation in breast, ovarian and hepatocellular cancer." (PMID 30359286, 2018). "Moreover, THBS1 and UCHL1 methylation in the serum was closely correlated with worse clinical outcomes in gastric cancer patients." (PMID 26550574, 2015). "However, studies on the molecular mechanism and role of UCHL1 in gastric cancer are very limited." (PMID 41155583, 2025). "Further, we identified 5 prognostic genes (RDH13, CLDN11, TMTC1, UCHL1, and FOXP2) in gastric cancer." (PMID 34322159, 2021). "We revealed that RDH13, CLDN11, TMTC1, UCHL1, and FOXP2 can serve as predictive biomarkers for gastric cancer treatment and the promoter methylation level of these five genes in serum could have prognostic and diagnostic functions in gastric cancer patients." (PMID 34322159, 2021).